FEN1 (flap structure-specific endonuclease 1)
Diseases named in the same sentence as FEN1 in open-access papers (continued):
Sharing a sentence is not in itself a finding about the gene and the disease.
lung carcinoma (continued). "The observation that FEN1 was up‐regulated in lung cancers was further confirmed in cancer cell lines." (PMID 28371273, 2017). "Manipulating the amount of FEN1 altered the response of lung cancer cells to chemotherapeutic drugs." (PMID 28371273, 2017). "We confirmed this observation by immunohistochemistry (IHC) assays comparing the FEN1 protein expression level on normal and lung cancer samples from surgical treatment." (PMID 28371273, 2017). "The FEN1 inhibitor significantly suppressed cell proliferation and induced DNA damage in lung cancer cells." (PMID 28371273, 2017). "In this study, we presented evidence that FEN1 was overexpressed in lung cancer and promoted tumor progression in vitro and in vivo." (PMID 28371273, 2017). "The results showed that FEN1 mRNA expression level in lung cancer tissues was significantly higher than that in normal tissues." (PMID 28371273, 2017). "Data from the TCGA database indicated that malignancy grade rose with increasing FEN1 expression levels in lung cancers, suggesting that the malignancy of lung cancer was correlated with FEN1 overexpression." (PMID 28371273, 2017). "Lung cancer cell lines (A549, H1299, and H460) displayed significantly higher FEN1 expression level than the normal lung cell line (HELF)." (PMID 28371273, 2017). "Down‐regulation by siRNA or inhibition FEN1 activity by small‐molecule inhibitor suppressed cell proliferation and sensitized lung cancer cells to cisplatin." (PMID 28371273, 2017). "In mouse models, the FEN1 inhibitor sensitized lung cancer cells to a DNA damage‐inducing agent and efficiently suppressed cancer progression in combination with cisplatin treatment." (PMID 28371273, 2017). "How FEN1 was altered also dictated how the lung cancer cells responded to chemotherapeutic drugs." (PMID 39796653, 2024). "FEN1 is highly upregulated in prostate, ovarian, breast, and lung cancers." (PMID 37326412, 2023). "Additionally, FEN1 inhibitors sensitise lung cancer cells to cisplatin and efficiently suppress cancer progression." (PMID 37326412, 2023). "In addition to its high expression in cervical cancer, FEN1 is overexpressed in many tumours such as breast and lung cancer." (PMID 35379200, 2022). "Upstream regulatory mechanisms of FEN1 in lung cancer was investigated in this study." (PMID 33827468, 2021). "Furthermore, upregulation of PRMT1 correlates with high expression of FEN1 in lung cancer due to stabilization of the FEN1 protein via PRMT1-mediated arginine methylation." (PMID 34006904, 2021). "Indeed, our previous data showed that FEN1 overexpression protected lung cancer cells from apoptosis induced by a DNA damaging drug cisplatin." (PMID 31670906, 2019). "In view of the role of FEN1 in DNA replication, we speculated that FEN1 might be essential for cell proliferation of lung cancers." (PMID 28371273, 2017). "FEN1 has been reported to be overexpressed in lung cancer, testis and brain tumors, and altered FEN1 expression might impact the therapeutic response." (PMID 28371273, 2017). "To test this hypothesis, we performed drug‐sensitive experiments in A549 lung cancer cells with different FEN1 levels." (PMID 28371273, 2017). "In this work, we found that flap endonuclease 1 (FEN1) is overexpressed in lung cancer cells." (PMID 28371273, 2017). "Our study suggests that targeting FEN1 may be a novel and efficient strategy for a tumor‐targeting therapy for lung cancer." (PMID 28371273, 2017). "We showed that FEN1 is critical for the rapid proliferation of lung cancer cells." (PMID 28371273, 2017). "Furthermore, FEN1 inhibitor impeded the progression of lung cancer and resulted in an accumulative effect when combined with cisplatin in vitro and on xenograft tumor mice models." (PMID 28371273, 2017). "The fact that FEN1 is involved in NER and other DNA repair pathways prompted us to further speculate that targeting FEN1 could be a potential way to overcome the drug resistance of lung cancer to cisplatin." (PMID 28371273, 2017).
lung carcinoma (continued). "This study indicates that although FEN1 polymorphisms, c.-69G>A (rs174538) and c.4150G>T (rs4246215) are not genetically associated with FECD, its transcript regulation in FECD and other diseases such as lung cancer could be mediated through miRNA." (PMID 30260965, 2018). "Our work showed that targeting FEN1 could be a potential strategy for lung cancer therapy." (PMID 28371273, 2017). "Human 8-oxoguanine DNA glycosylase (hOGG1) is relative to DNA oxidative damage and repair, and flap structure-specific endonuclease 1 (FEN1) plays a crucial role in DNA replication and cell proliferation, both of which are promising biomarkers in lung cancer." (PMID 38188023, 2023). "PRMT1 knockdown decreases FEN1 expression and increases DNA damage in A549 lung cancer cells treated with Temozolomide (TMZ) or 5-fluoro-uracil, which can be partially rescued by overexpressing FEN1." (PMID 36077176, 2022). "To evaluate the toxicity of FEN1 inhibitor on cells with different FEN1 levels, we compared the IC50 of C20 among various lung cancer cell lines." (PMID 28371273, 2017). "Flap endonuclease 1 (FEN1), playing a key role in DNA replication and repair, is maintained at high expression levels by PRMT1, crucial for DNA repair and chemotherapy resistance in lung cancer cells." (PMID 38525426, 2024). "Clinical effect of FEN1 and RAD54B in lung cancer death patients." (PMID 26431531, 2015).
gastric cancer (23 papers, 2015 to 2025). A primary or metastatic malignant neoplasm involving the stomach. "FEN1 has been implicated in the malignancy progression of various cancers, including gastric cancer, NSCLC, and cholangiocarcinoma." (PMID 38962012, 2024). "In addition, FEN1 was overexpressed in gastric cancer and FEN1 expression was associated with clinicopathological characteristics." (PMID 38396787, 2024). "Similarly, a study had confirmed that the expression of FEN1 in gastric cancer was positively associated with the degree of differentiation, lymphatic metastasis, tumor size and TNM stage (Wang, Xie & Chen, 2014)." (PMID 31534853, 2019). "For instance, in gastric cancer, FEN1 levels are higher when compared to normal tissue, with elevated expression correlating to poor prognoses for patients." (PMID 40612863, 2025). "Research has indicated that modulating FEN1 expression can alter sensitivity to cisplatin in both breast and gastric cancers." (PMID 40612863, 2025). "In their study, analysis of FEN1-mRNA and protein expression using semiquantitative reverse transcription-PCR and IHC in paired samples of gastric cancer and corresponding normal tissues demonstrated FEN1 overexpression in gastric cancer." (PMID 34809722, 2021). "Our data would concur with previous studies in LN308 glioma cells and in SGC-7901 gastric cancer cells where FEN1 depletion also increased platinum sensitivity and lead to the accumulation of DSBs." (PMID 33919707, 2021). "FEN1 expression had a positive correlation with differentiation degree, lymphatic metastasis, tumor size, and gastric cancer stage." (PMID 34277392, 2021). "Wang K discovered that about 76% human gastric cancer tissues had higher FEN1 expression in comparison to the corresponding normal gastric tissues." (PMID 32586310, 2020). "The results showed that Jianpi Yangwei Decoction inhibited DNA damage repair of gastric cancer by reducing FEN1 expression to reverse 5-Fu resistance to gastric cancer." (PMID 32586310, 2020). "This study aimed to explore the role of FEN1-mediated DNA damage repair in the drug resistance of gastric cancer and the effect of JPYW on it by employing BGC823/5-Fu drug-resistant cell model." (PMID 32586310, 2020). "In the meantime, existing studies have shown that FEN1 is highly expressed in gastric cancer, which is closely related to the prognosis of gastric cancer." (PMID 32586310, 2020). "FEN1 was highly expressed in drug-resistance gastric cancer cells BGC823/5-Fu, which leading to BGC823 resistant to (5-Fu) by acting on DNA damage repair." (PMID 32586310, 2020). "It is one of the potential tumor markers for gastric cancer, and reducing the FEN1 expression can effectively improve the chemotherapy sensitivity of gastric cancer." (PMID 32586310, 2020). "The study indicated that inhibiting FEN1 was one of the effective ways to improve the gastric cancer’s sensitivity to chemotherapy." (PMID 32586310, 2020). "Recent studies showed that FEN1 depletion enhanced the cytotoxic effects of cisplatin in the lung, breast and gastric cancer cells." (PMID 31402791, 2019). "Abdel-fatah and colleagues investigated this relationship in a cohort of gastric cancer patients and found a correlation of high expression of FEN1 and lymph node positive disease with poor disease survival." (PMID 26431531, 2015). "In breast, ovarian, and gastric cancers, Fen1 has been attempted as a key biomarker." (PMID 40685548, 2025). "Furthermore, studies have also shown that alterations in the expression and activity of certain enzymes involved in DNA repair, such as PARP1 and FEN1, can contribute to the development of genomic instability in gastric cancer." (PMID 38127056, 2023). "In conclusion, FEN1 was highly expressed in drug resistance gastric cancer cells BGC823/5-Fu, leading to the increase of DNA damege repair level and the reduction of 5-Fu chemotherapy sensitivity, which made it an important factor in drug resistance of gastric cancer." (PMID 32586310, 2020).
gastric cancer (continued). "Over expression of FEN1 observed in cancer cells like gastric, lung, neuroblastoma, pancreatic and prostate cancer and also observed the low level of FEN1 expression in some cancer cells like colorectal esophageal and gastric cancer." (PMID 28187440, 2017). "However, previous reports have demonstrated that the down‐regulation of FEN1 can increase the sensitivity of cisplatin in LN308 glioma cells and SGC‐7901 gastric cancer cell, implying the involvement of FEN1 in the repair of cisplatin‐induced DNA damage." (PMID 28371273, 2017). "Similarly, knock out of FEN1 enhances the sensitivity of gastric cancer cells to cisplatin." (PMID 33827468, 2021). "For example, hsa-miR-140-5p directly targets FEN1 and YES1 in cervical and gastric cancer, respectively, thereby inhibiting cancer cell proliferation, migration, and invasion." (PMID 39684278, 2024). "In summary, we confirmed that FEN1 expression level was directly related to BGC823’s resistance to 5-Fu, and it was a key gene in the 5-Fu resistance of gastric cancer cells relevant to DNA damage repair." (PMID 32586310, 2020). "Moreover, FEN1 expression had a positive correlation with the degree of differentiation, lymphatic metastasis, tumor TNM stage of gastric cancer." (PMID 32586310, 2020). "Flap Endonuclease 1(FEN1) has been considered as a new tumor marker in recent years and Jianpi Yangwei Decoction (JPYW) is a basic Traditional Chinese Medicine (TCM) for the treatment of gastric cancer." (PMID 32586310, 2020).
hepatocellular carcinoma (18 papers, 2019 to 2025). A malignant tumor that arises from hepatocytes. "Only recently FEN1 was recognized as a key enzyme for hepatitis B virus cccDNA formation and as a marker for hepatitis B virus-associated hepatocellular carcinoma." (PMID 33770148, 2021). "Overexpression of Flap endonuclease 1 (FEN1) has been previously implicated in hepatocellular carcinoma (HCC), while its expression features and mechanisms remain unclear." (PMID 35173534, 2022). "IGF2BP2 was proved to act as an oncogene, and maintained FEN1 expression through an m6A- dependent mechanism in hepatocellular carcinoma cells." (PMID 36358640, 2022). "Similarly, in hepatocellular carcinomas, FEN1 expression may be linked to poor prognosis." (PMID 33919707, 2021). "FEN1, a direct target of miR-140-5p, is related to the epithelial-mesenchymal transition of hepatocellular carcinoma cells." (PMID 32536819, 2020). "We confirmed these findings in vitro, showing that FEN1 mRNA and protein levels were significantly higher in the five human hepatoma cell lines (MHCC97-H, HepG2, SMMC-7721, HCCLM3 and Huh-7) compared to the normal HL7702 cells." (PMID 31402791, 2019). "FEN1 overexpression was further confirmed in hepatoma cell lines and we demonstrated its ability to promote hepatoma cell metastasis in vitro and in vivo by inducing EMT." (PMID 31402791, 2019). "In addition, our results showed that FEN1 was elevated in six human hepatoma cell lines relative to a control cell line via RT-qPCR analysis, which provided some basis for further study of the function of FEN1 in liver cancer." (PMID 31534853, 2019). "Furthermore, FEN1 mRNA levels were found significantly elevated in six human hepatoma cell lines relative to that in the normal human liver cell line, HL7702." (PMID 31534853, 2019). "In hepatocellular carcinoma, IGF2BP2 directly recognizes and binds to the m6A site of the FEN1 mRNA, increased the stability of FEN1 mRNA, and promotes the proliferation of hepatocellular carcinoma cells." (PMID 35299748, 2022). "Another study showed that METTL3 catalyzes m6A modification of FEN1 mRNA, which is recognized and stabilized by IGF2BP2 in hepatocellular carcinoma cells." (PMID 35502895, 2022). "Flap Endonuclease 1 (FEN1) is a known oncogene in an array of cancers, but its role in hepatocellular carcinoma (HCC) remains obscure." (PMID 31402791, 2019). "FEN1 expression in HCC and other tumor types was assessed with the FIREBROWSE and ONCOMINE databases, and results were verified in HCC samples and hepatoma cells." (PMID 31534853, 2019). "In the current study, we detected a higher expression of FEN1 in hepatocellular carcinoma tissues relative to adjacent nontumor tissues." (PMID 32399086, 2020). "Previous studies have shown that FEN1 plays an important role in the development of hepatocellular carcinoma, however, the molecular mechanisms remain fully elucidated, especially its effect on the cell cycle of hepatocellular carcinoma has not been investigated." (PMID 38230217, 2024). "To explore the clinical significance of FEN1 in distinguishing hepatocellular carcinoma tissues from normal ones in the liver, we analyzed the receiver operating characteristic (ROC) in four independent HCC cohorts." (PMID 32399086, 2020).
liver cancer (17 papers, 2019 to 2024). An epithelial or non-epithelial malignant neoplasm that arises from the liver. "For example, IGF2BP2 maintains FEN1 expression through an m6A-dependent mechanism to promote liver cancer growth." (PMID 37744330, 2023). "Overexpressed IGF2BP2 can directly recognize and bind to the m6A site of FEN1 mRNA, enhancing the stability of FEN1 mRNA and promoting the proliferation of liver cancer cells in vitro and in vivo." (PMID 35784761, 2022). "For instance, IGF2BP2 presents a high expression in liver cancer tissues and facilitates liver cancer development via the m6a-Flap endonuclease 1 (FEN1)-dependent mechanism." (PMID 35014946, 2022). "Down-regulation of MiR-140-5p is required for TGF-β-induced liver cancer metastasis, and FEN1 is a direct target of MiR-140-5p." (PMID 35883563, 2022). "Based on these findings, we propose a model that highlights the role of FEN1 in regulating TGF-β signaling during liver cancer metastasis." (PMID 31402791, 2019). "The results revealed that FEN1 expression was clearly elevated in most cancers, including bladder, breast, colorectal, esophageal, lung, and liver cancer." (PMID 31534853, 2019). "IGF2BP2 interacts with and stabilizes FEN1 mRNA from decay in liver cancer." (PMID 37142269, 2023). "IGF2BP2 promotes the liver cancer growth via FEN1; however, its role in iron metabolism remains unclear." (PMID 37088822, 2023). "IGF2BP2 could directly recognize and bind to the m6A site of FEN1 mRNA, enhance the stability of FEN1 mRNA and promote the progression of liver cancer." (PMID 35883563, 2022). "As expected, FEN1 expression was significantly positively correlated with that of MCM2, RFC4, and BIRC5 in TCGA liver cancer tissues, suggesting that FEN1 may be as involved in the development of HCC as are MCM2, RFC4, and BIRC5." (PMID 31534853, 2019). "Furthermore, the expression of FEN1 was positively correlated with that of three other core genes in TCGA liver cancer tissues." (PMID 31534853, 2019). "Interestingly, a correlation analysis revealed that high expression of FEN1 was significantly correlated with tumor size, metastasis and vascular invasion, suggesting that FEN1 may be involved in the regulation of liver cancer proliferation and metastasis." (PMID 31534853, 2019). "For example, IGF2BP2 stabilizes flap endonuclease-1 (FEN1) transcripts methylated by METTL3, promoting liver cancer growth." (PMID 38809498, 2024). "In this study, we identified three NHEJ genes (FEN1, PRKDC and XRCC6) were upregulated in liver cancer tissue based on TCGA data." (PMID 37016451, 2023). "Overall, our study revealed that METTL3 and IGF2BP2, acting as an oncogene, maintained FEN1 expression through an m6A-IGF2BP2-dependent mechanism in HCC cells, and indicated a potential biomarker panel for prognostic prediction in liver cancer." (PMID 33224879, 2020). "Knowledge of the TGF-β1-miR-140-5p-FEN1 axis enhances our understanding of the TGF-β network and highlights FEN1 as a therapeutic target to dampen TGF-β signaling during liver cancer progression." (PMID 31402791, 2019). "The expression of FEN1 in TCGA liver cancer tissues was positively correlated with that of MCM2 (r = 0.853, P = 0.000), BIRC5 (r = 0.809, P = 0.000), and RFC4 (r = 0.852, P = 0.000), suggesting that FEN1 may play as important a role in the progression of liver cancer as do MCM2, BIRC5, and RFC4." (PMID 31534853, 2019).